AHR (aryl hydrocarbon receptor)
Diseases named in the same sentence as AHR in open-access papers (continued):
Sharing a sentence is not in itself a finding about the gene and the disease.
breast carcinoma (continued). "Kyn has been shown to promote growth in an AHR-dependent manner in several types of cancer cells, including colon and breast cancer cells; therefore, we assessed the functional importance of Kyn and the AHR activation in primary LM cells." (PMID 37607000, 2023). "In support of this, AHR positive breast cancer patients have a relatively better prognosis than those with AHR negative breast cancer." (PMID 37834026, 2023). "Al-Dhfyan and colleagues demonstrated that the activation of AhR/CYP1A1 in breast cancer MCF-7 cells by TCDD or 7,12-dimethylbenz[a]anthracene induces the overexpression of β-catenin and its downstream target cyclin D1 at mRNA and protein levels." (PMID 37232717, 2023). "In estrogen receptor α (ERα)-positive breast cancers, the ability of AhR to promote the degradation of ERα in a ligand-dependent manner drives antiproliferative effects, and this antiestrogenic activity represents one mechanism of tumor suppression." (PMID 37106727, 2023). "An earlier paper about breast cancer MCF-7 cells showed that the activation of AhR/CYP1A1 promotes chemoresistance through the triggering of Wnt/β-catenin and ALDH pathways, which mediate the development, maintenance, and self-renewal of CSCs." (PMID 37232717, 2023). "Activated AHR is reported to inhibit many ER-dependent responses; because of this, AHR agonists have been suggested as potential therapeutic targets for ERα+ breast cancer." (PMID 37834026, 2023). "First, to investigate the role of AHR in the function of CSCs from HER2-overexpressing breast cancer cells, we compared the mammosphere formation efficiency of HER2-5 cells with that of HER2-5/AHRKO cells." (PMID 36292946, 2022). "Our findings suggest that miR125b-2–3p is a tumor suppressor and AF upregulates miR125b-2–3p to disrupt mammospheres via mechanisms that rely at least partially on AhR in luminal A breast cancer cells." (PMID 35694715, 2022). "The xenobiotic metabolism aryl hydrocarbon receptor (AHR) signaling pathway and estrogen-dependent breast cancer signaling pathway related to steroid hormone metabolism were enriched, consistent with the KEGG analysis results." (PMID 36232834, 2022). "Galangin was found to inhibit the aryl hydrocarbon receptor and is considered a potential drug for treating breast cancer." (PMID 35282430, 2022). "Nuclear AhR present in GC tumor and immune cells, fibroblasts and endothelial cells, suggests an activation of AhR, as previously reported in breast cancer." (PMID 35203450, 2022). "One study reported that ROS levels in BRCA1 and basal-like breast cancer correlated with AhR expression and this increased expression of amphiregulin (AREG), a ligand for the epidermal growth factor receptor (EGFR)." (PMID 36428667, 2022). "Although endogenous expression and function of the AhR in breast cancer cells is variable, the effects of structurally diverse AhR ligands are primarily associated with selective inhibition of pro-oncogenic responses." (PMID 36428667, 2022). "The role of AhR in cancer stemness and breast cancer stemness more specifically is complex, influenced by mode of AhR activation, engagement with various signaling pathways and cell context." (PMID 36588678, 2022). "In support of its role as a breast cancer oncogene, AhR activation is sufficient to transform human mammary epithelial cells and promote their migration, invasion and epithelial-to-mesenchymal transition (EMT)." (PMID 36588678, 2022). "Expression of WNT5A/B and β-catenin were correlated with markers of the cancer stem cell (CSC) phenotype, and AHR-antagonist treatment of MDA-MB-231 or SUM149 breast cancer cells resulted in significantly lower levels of WNT5A RNA." (PMID 36077068, 2022).
breast carcinoma (continued). "We explore AhR’s function in shaping the tumor microenvironment, modifying immune tolerance, and regulating cancer stemness, driving breast cancer chemoresistance and metastasis." (PMID 36588678, 2022). "The role of AhR as a mediator of chronic inflammation in breast cancer has been recently reviewed elsewhere." (PMID 36588678, 2022). "For example, curcumin treatment induced the DNA-binding capacity of AhR in human mammary carcinoma cells while it exerts antagonistic properties by inhibiting AhR translocation in murine hepatoma cells." (PMID 36014759, 2022). "In this review, there is strong evidence that in a large number of breast cancer cell lines the AhR alone exhibits both pro-and anti-oncogenic activity or minimal activity based on results of knockdown experiments." (PMID 36428667, 2022). "It has been also reported that TCDD (via an AhR-dependent mechanism) regulates the Akt pathway in breast cancer stem cells through inhibition of PTEN phosphatase." (PMID 36077780, 2022). "These highly variable ligand-dependent results in breast cancer cells were observed for pharmaceuticals that were all AhR-active in liver and liver cancer cells, demonstrating that these compounds are SAhRMs." (PMID 36428667, 2022). "In advanced malignant breast carcinomas, AHR is shown to be constitutively active and several studies reveal that targeting AHR can offer a potential treatment option for breast cancer patients." (PMID 36185256, 2022). "It has been published that via preventing PTEN and stimulating β-Catenin and Akt pathways, the AhR/CYP1A1 signaling pathway affected the phenotypes of breast cancer stem cells, such as growth, development, renewal, and chemoresistance." (PMID 36685893, 2022). "In basal-like and BRCA1-related breast cancers, ROS expression was correlated with AhR levels and the expression of the chemokines CXCL1, CXCL2, and CCL5." (PMID 36588678, 2022). "By contrast, the expression of the chemokine C-X-C motif chemokine receptor 4 is downregulated by AhR agonist-mediated activity in breast cancer cells, suggesting an anti-metastatic effect of AhR activation." (PMID 35773697, 2022). "The present study analyzed the correlation of VEGF-B and AhR in different cells, including breast cancer, primary human acute myeloid leukemia, and lung cancer by using GEO data." (PMID 35773697, 2022). "The relationship between AhR activation and breast cancer-related death was recently assessed using an artificial intelligence tool to analyze the scientific literature, with strong evidence that AhR activation is an adverse outcome pathway in breast cancer." (PMID 36588678, 2022). "Several studies support a role for AhR ligands as inhibitors of breast cancer and this includes some studies in this laboratory on TCDD and related compounds as antiestrogens associated with ligand-dependent inhibitory AhR-ERα crosstalk." (PMID 36428667, 2022). "A previous study in breast cancer MCF-7 cells showed that activation of AhR/CYP1A1 increased the chemoresistance by activating the Wnt/β-catenin and ALDH pathways, pathways that mediate CSCs development, maintenance, and self-renewal." (PMID 35742838, 2022). "Early studies of breast cancer cell lines report that aryl hydrocarbon receptor (AHR)-mediated induction of CYP1B1 is higher in cells having a mesenchymal morphology." (PMID 36077068, 2022). "Further studies have elucidated AhR’s molecular contribution to carcinogenic progression and ratified the oncogenic role of AhR in breast cancer cells." (PMID 36588678, 2022). "In this review article, the role of the AhR and its ligands as inhibitors of breast cancer in cellular and in vivo models will be investigated." (PMID 36428667, 2022). "There are also studies where the AhR and other ligands or cellular factors play a pro-oncogenic role in breast cancer." (PMID 36428667, 2022).
breast carcinoma (continued). "The anti-apoptotic role of AhR was previously reported in breast cancer, UVB-irradiated human keratinocytes, and primary rat hepatocytes by inhibiting pro-apoptotic proteins." (PMID 35742838, 2022). "1, 1-Bis (31-indolyl) methane (DIM), the dimeric metabolite of indole-3-carbinol (I3C) binds the AhR and several studies confirm the activity of this compound as an inhibitor of breast cancer cell and tumor growth." (PMID 36428667, 2022). "In breast cancer models, the AhR pathway was described to control CSC proliferation, development, self-renewal and chemoresistance through activation of the β-catenin pathway." (PMID 35437333, 2022). "Approximately 2 decades ago, AhR was found to be overexpressed in mammary cancer in rats sparking curiosity as to its role in breast cancer progression." (PMID 36588678, 2022). "Some of these AhR active compounds were subsequently screened for their activity in breast cancer cells." (PMID 36428667, 2022). "Nevertheless, the expression of the AhR in breast cancer and in breast cancer cell lines offers the opportunity for investigating the potential for AhR ligands as chemotherapeutic agents for treating breast cancer." (PMID 36428667, 2022). "This review considers several mechanisms which link the tumor promoting effects of environmental pollutants with the AhR signaling pathway, contributing to the development and progression of breast cancer." (PMID 36588678, 2022). "Indolo-[3,2b}-carbazole is another AhR-active metabolite of I3C that inhibits breast cancer cell migration." (PMID 36428667, 2022). "In human breast cancer, high expression of AhRR, the dedicated AhR repressor, independently predicts prolonged metastasis-free survival, in agreement with our findings in PyMT mice." (PMID 36588678, 2022). "AhR–dependent mechanisms for the inhibition of breast cancer by AhR agonists are variable and include the downregulation of multiple genes/gene products such as CXCR4, MMPs, CXCL12, SOX4 and the modulation of microRNA levels." (PMID 36428667, 2022). "A significant heterogeneity of TAMCs in mammary tumors has been described and the activation of AhR has been shown to activate TAMs and induce the accumulation of MDSCs." (PMID 36588678, 2022). "The prenatal administration of TCDD altered mammary gland development and enhanced DMBA-induced mammary cancer formation, whereas AhR activation during pregnancy decreased DMBA-induced tumor promotion." (PMID 36428667, 2022). "Further AhRR overexpression or knockout of AhR in human breast cancer cells enhanced apoptosis induced by chemotherapeutics and inhibited the growth of mouse mammary tumor cells." (PMID 33763068, 2021). "Hexachlorobenzene reduced AhR mRNA expression by enhancing TGF‐β1 mRNA levels in human breast cancer cells, and TGF‐β1 reduced TCDD‐induced AhR gene expression in nontumorigenic prostate epithelial cells." (PMID 33522060, 2021). "The elevated levels of γH2AX observed in AhR-compromised breast cancer cells exposed to genotoxic drugs, supports previous studies showing that AhR plays an important role in repair of DSB." (PMID 33763068, 2021). "In accordance, AhR expression was shown to correlate with an invasive transcriptomic signature, and AhR inhibition reduced the metastatic potential of breast-cancer cells in zebrafish." (PMID 33451095, 2021). "Pharmacological inhibition of AhR has been achieved using the compound 3′,4′-dimethoxyflavone (3′,4′-DMF) on breast-cancer cells, blocking formation of the nuclear AhR complex." (PMID 33451095, 2021). "Studies in mammalian cells have shown that LAT1 is upregulated in neuroblastoma and Burkitt’s lymphoma cells via Myc and in breast cancer cells via aryl hydrocarbon receptor (AHR)-mediated signaling." (PMID 34780467, 2021). "DIM inhibits colon cancer by activating AhR (aryl hydrocarbon receptor), as well as inhibiting breast cancer, ovarian cancer, uterine cancer, and lung adenocarcinoma by normalizing the sex hormone metabolism." (PMID 34684330, 2021).
breast carcinoma (continued). "One cancer cell line that has been extensively studied with DIM is the MCF-7 human breast cancer cell line as, in addition to AHR, DIM impacts estrogen receptor (ER)-dependent signaling in these ER-regulated cells." (PMID 34660663, 2021). "For example, the small molecule YL-109 was shown to increase CHIP transcription in breast cancer cells (MDA-MB-231) via recruitment of aryl hydrocarbon receptor (AhR) upstream of the CHIP gene." (PMID 34867205, 2021). "Another SERM, raloxifene, induced apoptosis in ER– breast cancer cells, which implies that AhR also plays a role in the hormone-independent setting." (PMID 34094928, 2021). "Inhibition of the GSK3β activity suppresses the ligand-activated transcription of an AHR target gene in HeLa, human liver cancer (Hep3B), and human breast cancer (MCF-7) cells." (PMID 34198826, 2021). "In prior work, we demonstrated that overexpression of AhRR in vitro, in human breast cancer cells, inhibits cell survival mediated by AhR." (PMID 33763068, 2021). "In female rats, dioxin containing AHR agonist induces, the occurrence of breast cancer and uterine tumors, suggesting that AHR is related to the development of cervical cancer." (PMID 34784845, 2021). "Despite dysregulation of the AhR/AhRR axis in breast cancer, relatively little is known about the function of AhRR in vivo." (PMID 33763068, 2021). "For instance, Estrogen Receptor alpha agonists inhibit the activation of AHR in MCF-breast cancer cells." (PMID 34784845, 2021). "In vivo and in vitro data have shown that the activation of the AhR signaling pathway can inhibit the growth and/or migration of breast cancer, pancreatic cancer, and ovarian cancer." (PMID 34955744, 2021). "AHR is overexpressed in breast cancer, skin cancer, lung cancer, and other tumor tissues, suggesting that AHR is a potential target gene for the treatment of malignant tumors." (PMID 34784845, 2021). "The aryl hydrocarbon receptor (AhR) is a master regulator of multiple pathways involved in breast cancer, and influences the estrogen receptor alpha (ER) and aromatase/CYP19A1." (PMID 34094928, 2021). "Conversely to it, several studies have shown that AhR activation by endogenous or exogenous ligands leads to increased tumor-cell migration and aggressiveness in breast cancer and lung-cancer cell lines exposed to kynurenine and benzo(a)pyrene (BaP)." (PMID 33451095, 2021). "We find that expression changes in the AhR/AhRR axis observed in human breast cancer are reflected in this model, with overexpression of AhR and its canonical targets COX-2 and C/EBPβ along with down-regulation of AhRR." (PMID 33763068, 2021). "Activation of the aryl hydrocarbon receptor (AhR) through environmental exposure to known human carcinogens including dioxins can lead to the promotion of breast cancer." (PMID 33763068, 2021). "Using the AhRR transgenic mouse, we demonstrate that AhRR overexpression opposes AhR-driven and inflammation-induced growth of mammary tumors in two different murine models of breast cancer." (PMID 33763068, 2021). "In breast cancer, CAF-secreted kynurenine, a tryptophan metabolite, was found to promote E-cadherin/Aryl hydrocarbon receptor (AhR)/S-phase kinase-associated protein 2 (Skp2) complex, leading to E-cadherin degradation, which supported cancer cell invasion." (PMID 33540679, 2021). "More recently, we and other groups found that the AhR is frequently overexpressed in human breast cancer, particularly ER-negative breast cancer." (PMID 33763068, 2021). "While our results suggest that AhRR overexpression in the host environment is sufficient to decrease mammary tumor cell growth, the tumor cell-intrinsic vs. extrinsic roles of AhR/AhRR are complex and have to be explored in more detail." (PMID 33763068, 2021). "In the syngeneic E0771 model, we demonstrate that AhRR overexpression inhibits basal and AhR-driven (TCDD-stimulated) mammary tumor cell growth." (PMID 33763068, 2021).
breast carcinoma (continued). "Herein, we report the breast cancer selectivity of a novel naphthalimide class of compound and the role of the AHR pathway in this phenomenon." (PMID 32814815, 2020). "These experimental results suggested that emodin inhibited the proliferation of breast cancer cells by activating on AhR." (PMID 33542691, 2020). "CSC-dependent low adherence spheroid formation of choriocarcinoma or breast carcinoma cells in vitro was suppressed with AHR inhibitors or AHR knockdown and increased with AHR agonists (e.g., TCDD)." (PMID 33396563, 2020). "Others reported breast cancer cell-derived IL-1α up-regulated IL-22 production of T cells in an AhR- and RORγt-dependent manner, which indicated a direct crosstalk between cancer cells and immune cells." (PMID 32649314, 2020). "In 1997, Sovak group demonstrated a highly constitutive NF-κB expression in human breast primary and breast cancer cells and some years later, the same group reported that, together with AhR, NF-κB participates in the tumoral transformation of mammary cells." (PMID 32722276, 2020). "For example, polychlorinated biphenyl (PCB) interaction with the aryl hydrocarbon receptor (AHR) plays a major role in breast cancer." (PMID 33383938, 2020). "This study aimed to investigate the role of AhR in the effects of emodin treatment of MCF-7 breast cancer cells." (PMID 33542691, 2020). "The clinical relevance of the AhR/GPR30 interplay is validated by the observation of high mRNA expression levels of these two receptors in breast cancer patients as markers of poor prognosis." (PMID 32670863, 2020). "Regarding breast cancer subclasses, the AhR/GPR30 gene expression signature was more informative in the ER-negative (p = 0.001) than in the ER-positive (p = 0.41) or luminal subclasses and (p = 0.50)." (PMID 32670863, 2020). "Recent studies strongly support the use of the aryl hydrocarbon receptor (AhR) as a therapeutic target in breast cancer." (PMID 32085612, 2020). "In conclusion, we demonstrated that TFPI-2 levels were upregulated by miR-494 in the breast cancer cell line MCF-7 most likely by an indirect regulation involving the association between miR-494 and the transcription factors AHR and ELF-1." (PMID 32132611, 2020). "Meanwhile, AHR is a ligand-dependent transcription factor and has been found abnormally elevated in some tumors including breast cancer, non-small cell lung cancer, colon cancer and ovarian cancer." (PMID 32546278, 2020). "Retrospective analysis of two independent breast cancer cohorts revealed that the AhR/GPR30 mRNA expression signature resulted in poor breast cancer prognosis, in particular in the ER-negative and the triple-negative subtypes." (PMID 32670863, 2020). "Previous controversial studies emerged regarding the prognostic value of AhR or GPR30 expression levels in breast cancers, and these discrepancies have been suggested as possibly related to the breast cancer subgroup or the substage considered." (PMID 32670863, 2020). "Univariate analysis of the GPR30 mRNA expression levels, the AhR mRNA expression levels and the GPR30/AhR mRNA expression signature with regards to overall survival (OS) in different subclasses of the 113 breast cancer samples of the CLB cohort." (PMID 32670863, 2020). "DMBA (7,12-dimethylbenz-[α]-anthracene) is a commercial chemical agent used to induce breast cancer in preclinical models by activating cellular cytosolic receptor aryl hydrocarbon receptor (AhR)." (PMID 32698395, 2020). "Previous reports have shown that there are other flavonoid compounds that can selectively inhibit breast cancer cells by activating the AhR pathway." (PMID 33542691, 2020). "Omeprazole, a proton pump inhibitor, activates AhR and decreases breast cancer cell migration and invasion." (PMID 32085612, 2020).